IL1B (interleukin 1 beta)
Diseases named in the same sentence as IL1B in open-access papers (continued):
Sharing a sentence is not in itself a finding about the gene and the disease.
inflammatory bowel disease (continued). "Activation of the NLRP3 inflammasome induces the maturation and production of the proinflammatory cytokines interleukin 1β (IL-1β) and IL-18, which further induce inflammation in inflammatory bowel diseases." (PMID 34043726, 2021). "Elevated IL-1β levels are associated with an increase in inflammatory bowel disease (IBD) severity." (PMID 33716675, 2021). "Many cytokines such as TNF-α, IL-6, and IL-1β play a key role in the pathogenicity of inflammatory bowel disease, in regulating inflammation of the intestinal mucosa, and in the integrity of the intestinal epithelium." (PMID 33204254, 2020). "Cytokines such as IL-6, IL-8, MCP-1 and IL-1β are potent pro-inflammatory cytokines, and their elevated levels play crucial roles in the development of several diseases including diarrhea and inflammatory bowel diseases." (PMID 32150574, 2020). "Aberrant activation of pro-inflammatory myeloid cells and sustained production of inflammatory cytokines, such as IL-1β, play instrumental role in the pathogenesis of inflammatory bowel diseases, such as ulcerative colitis and Crohn’s Disease25–28." (PMID 33311467, 2020). "However, IL-1β dysregulation is associated with numerous diseases including inflammatory bowel disease (IBD) and auto-inflammatory conditions such as the cryopyrin associated periodic syndromes (CAPS)." (PMID 31139177, 2019). "The transcriptional factor NF-κB is known to regulate the level of TNF-α, IL-6, and IL-1β during the progression of inflammatory bowel disease." (PMID 29483924, 2018). "LPS-induced cytokines IL-1β, IL-6, and TNFα, which are also expressed in inflammatory bowel disease, are reported to down-regulate PXR and CYP genes in vivo." (PMID 27760163, 2016). "The proinflammatory cytokines IL-1β and TNF-α, associated with inflammatory bowel diseases, exert different effects on gut epithelial cells monitored by the secretion of different combinations of chemokines in CEC." (PMID 25944986, 2015). "In human inflammatory bowel disease, it is thought that IL-1β is expressed by macrophages in the inflamed colon." (PMID 26218284, 2015). "The differentiated macrophages are potent producers of key inflammatory cytokines such as TNFα, IL-1β and IL-6 in inflammatory bowel disease 50,51." (PMID 25754842, 2015). "In this context, it should be notes that increased concentrations of IL-1β and IL-2 have been reported in endoscopic mucosal biopsy specimens from patients with inflammatory bowel disease." (PMID 23497090, 2013). "Studies in inflammatory bowel disease demonstrated an impaired IL-4 mediated down-regulation of IL-1b, TNF alpha, and therefore leading to uncontrolled pro-inflammatory cytokine release." (PMID 23472217, 2013). "Of note, IL-25 and IL-33 have been reported to modulate the severity of various inflammatory diseases involving IL-1β secretion including allergic inflammation, autoimmunity and inflammatory bowel disease." (PMID 23935505, 2013). "Mice with targeted deletion of Gαi2 develop an inflammatory bowel disease closely resembling ulcerative colitis, and the IFNγ and IL1β levels were increased in the inflamed colons." (PMID 19238203, 2009). "Cytokines, including IL‐1β, IL‐6, and TNF‐α, are expressed at relatively higher levels in the intestinal tissues of patients with UC, and MPO‐mediated damage is associated with some disorders in people, including inflammatory bowel disease." (PMID 40586619, 2025). "IL-1β classical monocytes significantly enrich the heritability of inflammatory bowel disease." (PMID 40703454, 2025). "A recent study of pathotypes in inflammatory bowel disease showed an association of an IL-1β-activated fibroblast signature with a lack of response to multiple therapies." (PMID 37277655, 2023). "It has been reported that LPS could stimulate the TLR4-NF-κB signaling pathway to induce the release of TNF-α, IL-1β, and IL-6, which are inflammatory cytokines in inflammatory bowel disease." (PMID 37125181, 2023).
inflammatory bowel disease (continued). "IL-1β and IL-6 are part of the NF-κB pathway, they are important mediators of the inflammation at the level of the intestine and have been related to inflammatory bowel diseases." (PMID 35216089, 2022). "Furthermore, TNF-α treatment increased the expression of genes encoding various proinflammatory cytokines such as IL-6, IL-8, IL-1β, and IL-17C, involved in the progression of inflammatory bowel disease." (PMID 34208517, 2021). "In most inflammatory bowel diseases, IL-1β acts together with other proinflammatory cytokines such as IL-6 and tumor necrosis factor-α or IL-23 in the inflammatory process, and treatment alone against the proinflammatory effects of IL-1β has little effect." (PMID 33553436, 2021). "A similar study showed that human umbilical cord MSC-EVs reduced TNF-α, IL-1β, IL-6, iNOS, and IL-7 genes while increasing the expression of IL-10 gene in the colon tissues relieving inflammatory bowel disease’s symptoms in mice with dextran sulfate sodium induced colitis." (PMID 33613514, 2020). "Furthermore, very high levels of IL-1β have been reported in the intestines of patients suffering from inflammatory bowel diseases." (PMID 31935236, 2020). "IL-1β is also an important indicator for measuring the severity of inflammatory bowel disease." (PMID 33537033, 2020). "EVs isolated from MSCs used in the model of inflammatory bowel disease induced by tri-nitrobenzene sulfonic acid injection in rats, EVs derived from rat BM-MSCs attenuated colonic inflammation via a markedly decrease in IL-1β and an increase in IL-10 expression." (PMID 33613514, 2020). "Similarly, anti-IL-1β were also thought to ameliorate the symptoms of inflammatory bowel diseases, Crohn’s disease, and ulcerative colitis, and to attenuate the development of non-small cell lung cell (NSCLC) in smokers." (PMID 30558178, 2018). "Interestingly inflammatory bowel disease also exhibits a strong inflammatory response primarily from high levels of IL1β and other chemokines." (PMID 28328972, 2017). "Furthermore, IL-1β has been identified as a target for Inflammatory Bowel Disease treatment in multiple studies." (PMID 27447967, 2016). "IL-1β is also upregulated in the intestines of patients suffering from inflammatory bowel disease." (PMID 23935505, 2013). "More recently, it has been characterized as an inflammatory cytokine that is implicated in several pathologic intestinal conditions (e.g. colon cancer and inflammatory bowel disease) likely through induction of IL-1b, IL-6, IL-8, IL-12, TNFα, and other pro-inflammatory cytokines." (PMID 22829946, 2012). "The IL-1 family of cytokines, especially IL-1β and IL-1α, plays a critical role in the pathogenesis of various inflammatory disorders, including inflammatory bowel disease (IBD), atherosclerosis, ischemia/reperfusion injury, coronary artery disease, and PTB." (PMID 41227337, 2025). "Utilizing a proinflammatory cocktail of TNF-α, IL-6, and IL-1β to mimic the inflammatory environment of inflammatory bowel disease (IBD), we observed clear differences in the cellular responses to acute versus chronic inflammation." (PMID 39489847, 2024). "The superpathway of L-cysteine biosynthesis (mammalian) can produce L-cysteine to downregulate the production of pro-inflammatory cytokines like IL-6, TNF-α, interferon-γ (IFN-γ), and IL-1β in inflammatory bowel disease (IBD)." (PMID 38675747, 2024). "In general, inflammatory bowel disease (IBD) patients exhibit an excessive immune response to commensal bacterial antigens, resulting in the release of pro-inflammatory cytokines, such as IL-1β, TNF-α, IL-6, and IL-12." (PMID 37376017, 2023). "Finally, our evidence for a role of IRAK1 on synovial fibroblasts and emerging data on an IL-1β/neutrophil axis in patients with inflammatory bowel disease suggest that fibroblasts within other organs may show a similar phenotype." (PMID 35801586, 2022).
inflammatory bowel disease (continued). "It has been found that NLRP3 and its mediated production of IL-1β could promote the development of inflammatory bowel disease, which, eventually, might develop into gastrointestinal malignancies, thus suggesting that pyroptosis actions an essential part in this process." (PMID 35571569, 2022). "It has been clearly demonstrated that the aberrant production of inflammatory cytokines, such as TNF-α, IL-1β and IL-6, often observed in the gut of patients with inflammatory bowel disease (IBD), is a consequence of deregulated NF-κB signaling cascade." (PMID 33652555, 2021). "It is well known that IL1β mimics inflammatory conditions that occur in intestinal tract and that may drive the development of such inflammatory chronic diseases as cancer, or such inflammatory bowel diseases (IBD) as ulcerative colitis and Crohn’s disease." (PMID 33256057, 2020). "Pro-inflammatory cytokines, like tumor necrosis factor (TNF)α and interleukin-1β (IL-1β), significantly contribute to the inflammation observed in inflammatory bowel diseases (IBD)." (PMID 32664604, 2020). "Cannabigerol (CBG) has exhibited protective properties in a murine model of inflammatory bowel disease (IBD) by regulating cytokine (IL-1β, IL-10, and interferon-γ) levels and inhibiting inducible nitric oxide synthase (iNOS) expression." (PMID 33584697, 2020). "Intestinal expression of IL-1β and IL-18 is enhanced in inflammatory bowel disease (IBD) patients and blocking or deleting IL-18 can reduce intestinal damage in mice." (PMID 26053862, 2015). "Interleukin 1 beta (IL-1β) contributes to the development of inflammatory bowel disease (IBD) and is correlated with the severity of intestinal inflammation." (PMID 23577872, 2013). "The heatmap of molecules participate in the “inflammatory bowel disease” revealed higher expression of NF-κB1, IFN-γ, IL18, IL1B, and IL18RAP in Group AOSC than in Group CD-AOSC." (PMID 41438472, 2025). "The anti-inflammatory effect of SA was reported in inflammatory bowel disease, as it decreased inflammatory markers such as NF-κB, TNF-α, and IL-1β." (PMID 40426893, 2025). "Studies in patients with inflammatory bowel disease reported the role of Enterobacterales in increasing the levels of IL-8, tumor necrosis factor (TNF)-α, and IL-1β." (PMID 40218236, 2025). "For instance, in inflammatory bowel disease (IBD), an overactive cytokine response leads to chronic inflammation in the gut, driven by excessive production of TNF-α, IL-1β, and IL-6, which contribute to tissue damage and immune dysregulation." (PMID 40364844, 2025). "During the pathogenesis of inflammatory bowel disease (IBD), the formation of NETs can activate the production of various pro-inflammatory factors, such as IL-1β, TNF-α, and IL-17A." (PMID 40620701, 2025). "However, IL1B levels are also significantly elevated in patients with active inflammatory bowel disease (IBD), indicating that IL1B should be considered alongside other biomarkers for accurate differentiation of intestinal diseases." (PMID 38979413, 2024). "In inflammatory bowel disease and colorectal cancer, the NLRP1 inflammasome acts through IL-1β and IL-18." (PMID 39456655, 2024). "MAdCAM-1 is constitutively expressed by intestinal endothelial cells, and its expression is upregulated on inflamed venules in chronic inflammatory diseases (e.g., inflammatory bowel disease) and induced by TNF-α and IL-1β." (PMID 38338944, 2024). "In a mouse model of inflammatory bowel disease pre-treated with piperine, levels of MCP-1 and IL-1β were decreased." (PMID 36678600, 2023). "Pro-inflammatory cytokines play an essential role in the regulation of intestinal immunity, and among them, IL-1β, TNF-α, and IL-6 abnormalities are considered to be important in the pathogenesis of inflammatory bowel disease." (PMID 38139262, 2023).
inflammatory bowel disease (continued). "In a separate inflammatory bowel disease (IBD) murine model, OXTR knock-out mice displayed an increased number of pro-inflammatory cytokine transcripts encoding for TNF-α, IL-1β, and IL-6 and exhibited shorter villi and crypts in the intestinal mucosa, a sign of chronic inflammation." (PMID 38983562, 2022). "The inflammatory factors, represented by interleukin-1β (IL-1β), interleukin-6 (IL-6) and tumor necrosis factor-α (TNF-α), are ultimately responsible for the inflammation in inflammatory bowel disease (IBD), obesity and other inflammation-related diseases." (PMID 35954128, 2022). "Although IL-1β has an established role in pathophysiology of inflammatory bowel disease (IBD) and irritable bowel syndrome (IBS), studies on changes in IL-1β levels in patients with SIBO are rare." (PMID 35630404, 2022). "The NF-κB signaling pathway has an important role in inflammatory bowel disease, which induces the secretion of inflammatory cytokines (TNF-α, IL-1β, IL-12) and upregulates the expression levels of pro-inflammatory factors COX2 and oxidative stress markers." (PMID 35450077, 2022). "The inflammatory bowel disease index, i-NOS, NO, MDA, and COX-2 in colon tissues and TNF-α, MPO, and IL-1β in blood serums, were decreased in the treatment group as compared to the model group." (PMID 33499333, 2021). "Inflammatory disorders, such as RA, Crohn's disease and inflammatory bowel disease (IBD), have shown increased expression of TNF, IL-1β and IL-6, which contribute to joint erosion and tissue destruction." (PMID 32873150, 2020). "In inflammatory bowel disease (IBD), IL-34 protects the integrity of the intestinal epithelium, and IL-34-differentiated macrophages show decreased IL-1β and TNF-α expression." (PMID 30405534, 2018). "In a dextran sodium sulfate (DSS)-induced murine model of colitis, DSS treatment resulted in a significant increase in the expression levels of pro-inflammatory cytokines such as IL-1β, TNF-α, and IL-6, which play key roles in the pathogenesis of inflammatory bowel disease (IBD)." (PMID 40051564, 2025). "This approach helped us to explore potential interactions between tissues, suggesting that reduced IL-1β in PMN could limit IL-8 release in the epithelium, which is relevant to inflammatory bowel disease." (PMID 41374007, 2025). "Furthermore, exosomes from human umbilical cord mesenchymal stem cells reduced the severity of inflammatory bowel disease in mice by increasing IL-10 levels and decreasing TNF-α, IL-1β, and IL-6 in the colon tissues." (PMID 40822681, 2025). "Our findings suggest that resveratrol may exhibit anti-inflammatory effects in Inflammatory Bowel Disease (IBD) by increasing IL-10 levels and decreasing TNF-α, IL-6, IL-1β, and IL-8 levels." (PMID 38948464, 2024). "In line with this, the beneficial effects of the ethanolic extract of T. polium in an animal model of acute inflammation, and extract of T. persicum in animal model of inflammatory bowel disease were accompanied by high expression of IL-10 and low expression of TNF-α and IL-1β." (PMID 39452128, 2024). "A study indicated that the expression of ATF4 was decreased in inflamed intestinal mucosa of patients with active inflammatory bowel diseases, and overexpression of ATF4 down-regulated inflammatory factors including IL-1β and IL-6, while deprivation of ATF4 promotes intestinal inflammation." (PMID 38913045, 2024). "In their study of inflammatory bowel diseases in humans, the researchers found that the expression of the inflammatory cytokines IL-6, TNF-α, and IL-1β were, respectively, upregulated 2.266, 0.962, and 3.468 fold, in both Crohn’s disease and ulcerative colitis compared to healthy individuals." (PMID 38116527, 2023).
inflammatory bowel disease (continued). "In addition, EPS which were isolated from L. plantarum YW11 reduced the production of the proinflammatory cytokines (TNFα, IL-1β, IL-6, IFN-γ, IL-12 and IL-18) and up-regulated IL-10, and this resulted in an amelioration of inflammatory bowel disease symptoms." (PMID 36769176, 2023). "Cytokines IL-1β and IL-8 were reported to be involved in the restriction of Salmonella infection, whereas TNF-α was shown to be elevated in the intestinal mucosa of inflammatory bowel disease patients, which can lead to excess inflammation and gut injury." (PMID 38247473, 2023). "Seven genes IL10, IL4, IL6, IFNG, IL1B, TNF and IL17A, were engaged in Inflammatory bowel disease." (PMID 36989283, 2023). "Several pro-inflammatory cytokines, including IL-6, IL-1β, and interferon-γ, have been shown to induce DNA methylation, making epigenetic modulation of ion transport components a newly emerging area of interest for a deeper understanding of the pathogenesis of inflammatory bowel disease (IBD)." (PMID 35626748, 2022). "Besides, in inflammatory bowel disease, levels of IL-1β in MLNs increase significantly, and inhibition of NLRP3/IL-1β signal axis is thought to improve the symptoms of SAE." (PMID 35111693, 2021). "IL-1β is a key mediator of the inflammatory response and plays a major role on the pathogenesis of inflammatory bowel disease (IBD), consistent with the finding that IL-1β is up-regulated in IBD patients and IBD colonic macrophages release mature IL-1β on exposure to lipopolysaccharide (LPS)." (PMID 34943999, 2021). "Previous studies have revealed that the high production of IL-1β and IL-18, through the dysregulation of inflammasome activity during the microbial invasion or intestinal inflammation, plays a critical role in the pathogenesis of inflammatory bowel diseases (IBD) and colorectal cancer." (PMID 34571825, 2021). "In addition, the IL1B gene SNPs (rs1143643 and rs1143627) chosen in our study have been demonstrated to be associated with other autoimmune inflammatory diseases, such as RA, ASSD and inflammatory bowel disease (IBD)." (PMID 34867336, 2021). "The NRLP inflammasome activated by ZEN is responsible for the maturation and secretion of proinflammatory cytokines IL-1β and IL-18, which play a role in the etiology of non-specific inflammatory bowel diseases." (PMID 32471145, 2020). "In patients with inflammatory bowel disease, a large population of inflammatory cells infiltrated in the mucosa, excessive inflammatory cytokines including tumor necrosis factor (TNF)-α, interleukin (IL)-18, IL-6, IL-1β were secreted." (PMID 33240089, 2020). "Secondary cytokines such as TNF-α, IL-1β, and IL-6 are known to increase the presence of inflammatory cells in the colon tissue in response to primary Th1/Th17 immune responses in inflammatory bowel disease (IBD) thereby synergistically drawing the inflammatory milieu." (PMID 31683524, 2019). "The mechanism of Portulaca extract in alleviation of inflammatory bowel disease could be related to its regulation of inflammatory cytokines (TNF-α, IL-6, and IL-1β), transcription factors (NF-kB and PPAR-γ), and apoptosis." (PMID 29483924, 2018). "Indeed, in an experimental model of inflammatory bowel disease, CBG reduced IL-1β and IFN-γ levels in inflamed colons, while in a model of Huntington’s disease, CBG was able to decrease the expression of TNF-α and interleukin 6 (IL-6)." (PMID 29986533, 2018). "In particular, studies on human colonic epithelial cell lines as well as on intestinal tissues from patients with inflammatory bowel diseases revealed that inflammatory cytokines, such as TNF and IL-1β, promoted an up-regulation of NK1 receptor expression and a marked increase in SP release." (PMID 27295950, 2016). "Inflammatory bowel disease (IBD) and many other inflammatory disorders are characterized by elevated expression of pro-inflammatory cytokines, such as TNF-α, IL-6 and IL-1β." (PMID 40391223, 2025).